WNT5B (Wnt family member 5B)
Diseases named in the same sentence as WNT5B in open-access papers (continued):
Sharing a sentence is not in itself a finding about the gene and the disease.
cancer (continued). "Fifteen members of cancer pathways, including FOS, TGFα, FZD8, MMP1, laminin subunit gamma 2, PTGS2, laminin subunit beta 3, ITGA2, laminin subunit alpha 3, VEGFC, WNT2B, heat shock protein 90 beta family member 1, WNT5B, FGF5 and WNT3A, were up-regulated in the MC group." (PMID 30482199, 2018). "Cell morphology and p-MLC2 levels were assessed as amoeboid markers; ki-67 staining as a proliferative marker; WNT11, WNT5B and DAAM1 expression as non-canonical Wnt markers; and ALDH1A1, ALDH1A3, CD44, NANOG and OCT4 were evaluated as cancer stem cell-related markers." (PMID 33082334, 2020).
tumor (38 papers, 2008 to 2025). "The polymorphism rs2010851 in the 3′ UTR of WNT5B was shown to predict tumor recurrence in stage II colon cancer." (PMID 34017835, 2021). "Genomic deletion of WNT5B may imply tumor suppressor function, its loss relieving Wnt signaling of the competing inhibition, and allowing the pathway to exert its negative regulation of PPARγ and C/EBPα." (PMID 18784837, 2008). "We validated the expression of WNT5B protein by performing IHC on a commercially available OS tissue microarray (TMA) consisting of primary tumours from 40 individuals." (PMID 38689429, 2024). "The smaller tumour volume in control tumours compared to WNT5B KO tumours suggests that while WNT5B slightly decreases the primary tumour development, it significantly enhances metastasis, as well as cell density, within tumours." (PMID 38689429, 2024). "Control liver and lung metastatic OS tumour deposits were remarkable for significantly more cellularity and mitotic activity when compared with WNT5B KO metastases." (PMID 38689429, 2024). "All 10 DEGs found in the patients who lived in Sao Paulo city compared to the MRSP were associated with cell proliferation and tumor development (BMP4, CTNNBP1, DISP1, DVL1, ERBB4, PRLR, WNT5b, LEF1, PGR, and PTEN)." (PMID 36768749, 2023). "The current study results revealed the upregulation of four genes including ADAMTS18, CDKN2B, and FHIT as tumor suppressors and WNT5B as an oncogene in the patients." (PMID 35176183, 2022). "Wnt ligands that were expressed in both tumor cohorts included Wnt5a, Wnt5b, and Wnt7b foremost, in accordance with the reported expression of these ligands in mammary epithelium." (PMID 36106661, 2022). "The intergenic and intron regions at WNT5B have marked as two discrete peaks, which was accompanied with an enhanced expression of WNT5B in tumor." (PMID 35947334, 2022). "5, WNT5B had higher expression in sarcomatoid and mixed histology tumours compared to epithelioid tumours." (PMID 34580349, 2021). "Several studies have demonstrated that Wnt5B is involved in the proliferation and migration of tumor cells and have critical role in tumor lymph angiogenesis and lymph node metastasis through the regulation of epithelial-mesenchymal transition (EMT)." (PMID 30814912, 2019). "Ultrasound imaging further confirmed that the tumor growth after knockdown of WNT5B was significantly inhibited." (PMID 31462314, 2019). "We used RFP to monitor tumor growth, and found that knockdown of Wnt5b inhibited the tumor growth compared to the control." (PMID 31462314, 2019). "This subgroup within ER+ve tumours can also be observed with analysis of Wnt5b, where high expression predicts early recurrence, and where high expression is a marker of the basal-type phenotype." (PMID 23861811, 2013). "We also observed specific interaction between fibroblasts and malignant tumor cells through the interaction of WNT5B and WNT2B with its downstream receptor in the WNT signaling pathway, which has been linked to supporting tumor cell proliferation, metabolism, and metastasis." (PMID 40874228, 2025). "In contrast, control tumours metastasised much more than the WNT5B KO group." (PMID 38689429, 2024). "Interestingly, WNT5B KO tumours (primary and metastatic) had markedly less cell density than the control tumours, which likely explains the difference in photon flux." (PMID 38689429, 2024). "The striking difference in cellularity and spacing of the WNT5B KO tumours led us to hypothesise that glycosaminoglycans (GAGs) could be involved." (PMID 38689429, 2024). "Interestingly, the primary tumour growth rate was slightly lower in the control group than in the WNT5B KO group." (PMID 38689429, 2024). "Taken together, these data indicate that many genes distinguish tumor groups with distinct epithelial and mesenchymal features, such as WNT5B, as well as EPB41L4A and TGFBI, controlled epigenetically by an array of transcriptional factors delineated above and chromatin accessibility changes." (PMID 36973268, 2023).
tumor (continued). "We showed WNT5B upregulation in ccRCC tumor subpopulations with EMT features." (PMID 36973268, 2023). "We additionally observed WNT5B upregulation in the ccRCC EMT tumor subpopulation." (PMID 36973268, 2023). "We validated the WNT5B protein expression in a patient tumor with the EMT signature population, suggesting WNT5B might mediate the EMT process in ccRCC." (PMID 36973268, 2023). "Studies indicated that WNT5A might have tumor suppressive roles, at least in some contexts, whereas WNT5B activates the WNT pathway in BBC." (PMID 37584250, 2023). "WNT5B has also been shown to be secreted from tumor cells to induce tumor lymphangiogenesis." (PMID 34017835, 2021). "Six WNTs, including WNT5B, showed the opposite pattern of expression, suggesting that WNT5B may have anti-tumor activity in HCC." (PMID 34017835, 2021). "WNT5B was elevated both in the tumor and the patients’ serum." (PMID 24564888, 2014). "Thus, it is possible that paracrine WNT5B signalling from the immune system or tumour microenvironment could contribute to metastatic growth, as evidenced in ovarian CSCs." (PMID 38689429, 2024). "Comparative analysis revealed tumor-specific upregulation of GLRX3, IL1RN, and TNFRSF4 (p < 0.001), contrasting with downregulation of FCGRT, UBN2, and WNT5B in EC versus normal tissues." (PMID 40722666, 2025). "Transcriptome analysis of WNT pathway genes in AT/RT primary tissues and AT/RT cell lines indicated that the WNT family member 5B gene (WNT5B; MIM #606361) is significantly upregulated as compared with non-tumour brain samples." (PMID 40794298, 2025). "Further, we identified that WNT5B mRNA and protein correlate with the receptor ROR1 in primary tumours." (PMID 38689429, 2024). "For example, Wnt5a, Wnt5b, long non-coding ASMTL-AS1 in tumor cell exosomes all have the ability to activate YAP to promote tumor formation and development." (PMID 36123390, 2023). "Targeting WNT5B (and all WNTs) through the addition of WNT inhibitors pyrvinium pamoate (a CK1α activator) or LGK-974 (a Porcupine inhibitor) also reduced tumor growth and proliferation in vivo." (PMID 34017835, 2021). "In turn, WNT5B increased the expression of MMP-10, a matrix metalloproteinase that induces tumor progression and invasion." (PMID 34017835, 2021). "Tumor stroma-derived WNT ligands like WNT3 and WNT5B are critical factors that instigate invasive behavior, and induction of an EMT phenotype in tumor epithelial cells." (PMID 31324218, 2019). "We further knocked down Wnt5b in MDA-MB-231 and Bcap-37 cells, which significantly inhibited the tumor growth." (PMID 31462314, 2019). "All our findings suggested that WNT5B/MCL1 cascade is critical for TNBC and understanding its regulatory apparatus provided valuable insight into the pathogenesis of the tumor development and the guidance for targeting therapeutics." (PMID 24564888, 2014). "In addition, knockdown of WNT5B in MDA-MB-231 and Bcap-37 cells showed reduced tumor growth in BALB/c-nu mice compared with control cells." (PMID 34017835, 2021). "Next, we used the Tumor IMmune Estimation Resource (TIMER) to assess whether FGL2, ERI1 or WNT5B expression correlated with infiltrating immune cell levels in ESCA." (PMID 33323552, 2020). "However, we cannot preclude additional paracrine factors also contributing to tumor formation since transcripts for other secreted growth regulators (SOST, BMP7, BMP8A, WNT5B, WNT10B, and FGF21) exhibited increased abundance in SHP2-depleted pellet cultures." (PMID 24875294, 2014). "Our model system KO WNT5B from tumour cells and not the host environment." (PMID 38689429, 2024). "In addition, we validated vimentin and WNT5B using immunofluorescence staining in a tumor with EMT tumor cells compared to another tumor without EMT tumor cells." (PMID 36973268, 2023). "Similarly, WNT5B expression did not correlate significantly with ESCA tumor purity, and only correlated weakly with the infiltrating levels of macrophages (r = 0.239, P = 1.21e-03)." (PMID 33323552, 2020).
tumor (continued). "We checked for changes in expression of Wnt ligands, and although there was a trend toward significantly increased expression of Wnt2, Wnt5b, Wnt8b, and Wnt10b specifically in the tumor and not the neighboring normal tissue, the changes did not quite reach statistical significance (Fig EV2A and B)." (PMID 28183841, 2017). "Indeed, Wnt ligand signaling plays a key role in PDAC progression and therapeutic resistance, and tumor-proximal fibroblasts are seen to be strong contributors to the Wnt ligand pool with high level expression of the ligands WNT5A, WNT11, WNT2, WNT5, WNT5A, and WNT5B." (PMID 37350578, 2023).
hematological cancers (1 paper, 2022). "WNT5b and WNT11 have been shown to regulate the non-canonical WNT pathway in non-hematological cancers." (PMID 35246138, 2022).
infection (1 paper, 2019). The state of being infected such as from the introduction of a foreign agent such as serum, vaccine, antigenic substance or organism. "Human cytomegalovirus (HCMV) infection of human foreskin fibroblasts was associated with WNT5A and WNT5B downregulation, whereas HCMV infection elevated WNT2 expression in human mesenchymal stem cells." (PMID 31781093, 2019). "With Wnt5a expression reported to be suppressed by S. pneumoniae and P. aeruginosa infection of macrophages, roles of other WNT ligands responsive to infection (e.g., Wnt4, Wnt5b, Wnt7a, Wnt7b) and the net-outcome of WNT signaling in infected cells will need further exploration." (PMID 31781093, 2019).
lip (1 paper, 2023). "In Family 15, the child with bilateral cleft lip and palate carries a rare missense (p.Arg88Leu) heterozygous nucleotide variant (c.263G > T) in exon 3 (rs200966877) inherited from the father on chromosome 12 of WNT family member 5B (WNT5B) gene." (PMID 36980938, 2023).
WNT5B also shares sentences with these, for which no sentence is quoted: osteoarthritis (3 papers); basal cell carcinoma (1); bladder cancer (1); brain tumors (1); coronary heart disease (1); diarrheal disease (1); Duchenne muscular dystrophy (1); Dystonia (1); Huntington disease (1); invasive breast carcinoma (1); ischemic stroke (1); kidney disease (1); Mcc (1); metastatic melanoma (1); neuroblastoma (1); neurodegenerative disease (1); non-small cell lung carcinoma (1); respiratory infection (1); rheumatoid arthritis (1); sarcopenia (1); schizophrenia (1); Thrombocytopenia (1); ulcerative colitis (1); viral hepatitis (1).